RNF186 (ring finger protein 186)
Description:
E3 ubiquitin protein ligase that is part of an apoptotic signaling pathway activated by endoplasmic reticulum stress. Stimulates the expression of proteins specific of the unfolded protein response (UPR), ubiquitinates BNIP1 and regulates its localization to the mitochondrion and induces calcium release from the endoplasmic reticulum that ultimately leads to cell apoptosis. Plays a role in the maintenance of intestinal homeostasis and clearance of enteric pathogens. Upon NOD2 stimulation, ubiquitinates the ER stress sensor activating transcription factor 6/ATF6 and promotes the unfolded protein response UPR. Participates in basal level of autophagy maintenance by regulating the ubiquitination of EPHB2 and EPHB3. Upon stimulation by ligand EFNB1, ubiquitinates EPHB2 and further recruits MAP1LC3B for autophagy induction. Controls nutrient sensing by ubiquitinating Sestrin-2/SESN2, which is an intracellular sensor of cytosolic leucine and inhibitor of mTORC1 activity.
Synonyms: FLJ20225
Tractability: Antibody: UniProt predicts a signal peptide or a membrane-spanning region. PROTAC: UniProt records ubiquitination sites on it.
Gene: Protein-coding gene on chromosome 1 (19,814,029 to 19,815,283, reverse strand). Ensembl gene ENSG00000178828.
Subcellular location: Endoplasmic reticulum membrane
Gene Ontology:
Molecular function: protein binding; ubiquitin protein ligase activity; ubiquitin protein ligase binding; ubiquitin-protein transferase activity
Biological process: intrinsic apoptotic signaling pathway in response to endoplasmic reticulum stress; proteasome-mediated ubiquitin-dependent protein catabolic process; protein autoubiquitination; protein K29-linked ubiquitination; protein K63-linked ubiquitination; protein localization to mitochondrion; protein ubiquitination
Cellular component: endoplasmic reticulum; endoplasmic reticulum membrane
Genetic constraint (gnomAD): Loss-of-function variants: 2 observed, 2.04 expected, observed/expected ratio (o/e) 0.98, 90% interval 0.36 to 1.87. That is too few expected variants to judge how well the gene tolerates losing a copy. Missense variants: 298 observed, 313.22 expected, observed/expected ratio (o/e) 0.95, 90% interval 0.87 to 1.05. Synonymous variants: 152 observed, 139.25 expected, observed/expected ratio (o/e) 1.09, 90% interval 0.96 to 1.25.
Homologues: Orthologues: chimpanzee RNF186 (99% identical), macaque RNF186 (94% identical), dog RNF186 (73% identical), rat Rnf186 (70% identical), rabbit RNF186 (69% identical), mouse Rnf186 (68% identical).
Diseases named in the same sentence as RNF186 in open-access papers:
RNF186 is named in the same sentence as 17 diseases in open-access papers, as found by Europe PMC text mining. Sharing a sentence is not in itself a finding about the gene and the disease. The quoted sentences say what the papers report.
ulcerative colitis (4 papers, 2013 to 2025). An inflammatory bowel disease involving the mucosal surface of the large intestine and rectum. "In the present study, we report the RNF186 germline mutation as an ulcerative colitis–related germline mutation." (PMID 40230421, 2025). "Compared with ulcerative colitis patients, South Asian individuals showed significantly different genotype and allele distributions of the A64T (rs41264113) variant of the RNF186 gene (p < 0.05)." (PMID 40230421, 2025). "In conclusion, we found the A64T variant of the RNF186 gene only in Korean ulcerative colitis patients." (PMID 40230421, 2025). "Additionally, we identified significantly different distributions of the A64T variant of the RNF186 gene between Korean ulcerative colitis patients and South/East Asian populations." (PMID 40230421, 2025). "In addition, East Asian patients showed significantly different allele distributions of A64T (rs41264113) in RNF186 gene compared with ulcerative colitis patients (p < 0.05)." (PMID 40230421, 2025). "In addition, the two genetic variants A64T (rs41264113) and R179X (rs36095412) that result in an altered form of RNF186 protein were shown to be associated with the pathomechanism of ulcerative colitis in a Caucasian population." (PMID 40230421, 2025). "In the present study, we investigated the genetic distributions of the two genetic variants A64T (rs41264113) and R179X (rs36095412) in the RNF186 gene and performed association analysis to identify the relationships between these genetic variants and susceptibility to ulcerative colitis." (PMID 40230421, 2025). "Furthermore, RNF186 gene variants have been shown to be associated with ulcerative colitis in humans." (PMID 33308304, 2020). "A previous genome-wide association study (GWAS) reported that the ring finger protein 186 gene (RNF186) is a potent pathogenesis-related factor of ulcerative colitis." (PMID 40230421, 2025). "Here, the authors screened in ulcerative colitis (UC) patients' genomes for protein-truncating variants near IBD loci, and identify a protein truncating variant in RNF186 to be protective against UC." (PMID 27503255, 2016). "In contrast, we did not observe the R179X variant of the RNF186 gene in either ulcerative colitis patients or matched healthy controls." (PMID 40230421, 2025).
bladder cancer (3 papers, 2022 to 2025). "OTUD5 can activate the mTOR signalling pathway by deubiquitinating ring finger protein 186 (RNF186), thereby promoting the progression of bladder cancer." (PMID 38658981, 2024).
colitis (3 papers, 2019 to 2021). Inflammation of the colon. "With respect to high sensitivity to DSS-induced colitis, RNF186 deficiency led to disturbed proteostasis and thus increased endoplasmic reticulum (ER) stress in IECs." (PMID 34956195, 2021). "Recently, it has been reported that RNF186 knockout mice were found to have increased bacterial loads in their mesenteric lymph nodes and spleen during DSS-induced colitis, and RNF186-deficient macrophages were impaired in bacterial phagocytosis and intracellular bacterial clearance." (PMID 34956195, 2021). "In addition, increased sensitivity to DSS colitis in Rnf186-/- mice was linked to reduced autophagy in the colonic epithelia attributed to RNF186 mediating K27-linked ubiquitination of EphB receptor B2 (EPHB2) at K892 site and further recruiting MAP1LC3B for autophagy." (PMID 34956195, 2021). "Notably, RNF186 functions differently in a dextran sulfate sodium- (DSS-) induced mouse model of colitis: RNF186-deficient mice develop more severe colitis during DSS administration, and their colonic epithelial cell exhibits enhanced signs of ER stress and apoptosis." (PMID 32848509, 2020). "Meanwhile, Rnf186-/- mice showed increased colon permeability to organic solutes and high sensitivity to DSS-induced colitis." (PMID 34956195, 2021). "Another RNF family gene, RNF186, was significantly decreased in the acute DSS colitis model." (PMID 31889078, 2019).
inflammatory bowel disease (2 papers, 2020 to 2021). A spectrum of small and large bowel inflammatory diseases of unknown etiology. "Notably, RNF186-A64T mutation is a risk factor for the development of ulcerative colitis (UC), a kind of inflammatory bowel disease (IBD)." (PMID 33670113, 2021). "Among these genes, previous studies had reported that FNDC4 (fibronectin type III domain containing 4), RNF186 (ring finger protein 186), and UBASH3A (ubiquitin associated and SH3 domain containing A) were associated with inflammatory bowel disease." (PMID 33043022, 2020).
Obesity (2 papers, 2020 to 2022). Accumulation of substantial excess body fat. "The major goal of the current study was to explore the function of liver RNF186 in the regulation of insulin tolerance and obesity-associated NAFLD." (PMID 35198905, 2022). "In conclusion, RNF186 deficiency in liver protected against obesity and in turn liver steatosis, insulin resistance, and hepatic inflammation induced by an HFD." (PMID 35198905, 2022). "Here, we found that hepatocyte-specific RNF186 knockout (RNF186LKO) mice were protected from HFD-induced obesity." (PMID 35198905, 2022). "The collective results suggested that ablation of RNF186 in liver significantly ameliorated hepatic steatosis-induced HFD-induced obesity." (PMID 35198905, 2022). "Moreover, the expression of Rnf186 has been shown to be induced in the livers of mice with diabetes, obesity, and diet-induced obesity." (PMID 32486221, 2020). "The collective results suggest that RNF186 may be a potential regulator of NAFLD in obesity." (PMID 35198905, 2022).
chronic kidney disease (1 paper, 2023). Impairment of the renal function secondary to chronic kidney damage persisting for three or more months. "Single nucleotide polymorphisms (SNPs) at the RNF186 locus (p.R179X) have been directly linked to elevated serum creatinine levels and chronic kidney disease in a genome-wide association study conducted on Icelandic individuals, and RNF186 R179X has been characterized as a loss-of-function mutation." (PMID 37137894, 2023).
colorectal cancer (1 paper, 2022). A primary or metastatic malignant neoplasm that affects the colon or rectum. "Another research team has found that RNF186 can negatively regulate NF-kappaB in colorectal cancer." (PMID 36085200, 2022).
Crohn disease (1 paper, 2018). A gastrointestinal disorder characterized by chronic inflammation involving all layers of the intestinal wall, noncaseating granulomas affecting the intestinal wall and regional lymph nodes, and transmural fibrosis. "For instance, PTVs in CARD9, RNF186 and IL23R provide protection against Crohn’s disease and/or ulcerative colitis and PTVs in ANGPTL4, PCSK9, LPA, and APOC3 protect against coronary heart disease." (PMID 29691392, 2018).
Hyperglycemia (1 paper, 2022). An increased concentration of glucose in the blood. "Altogether, RNF186 KO mice are protected against HFD-induced weight gain and associated fatty liver, insulin resistance, and hyperglycemia." (PMID 35198905, 2022).
Insulin resistance (1 paper, 2022). Increased resistance towards insulin, that is, diminished effectiveness of insulin in reducing blood glucose levels. "Hepatocyte-specific RNF186 KO mice were protected from hepatic insulin resistance induced by HFD feeding for 18 weeks." (PMID 35198905, 2022). "Deletion of RNF186 alleviated insulin resistance and ER stress induced by a high-fat diet (HFD), leading to a decrease in the expression of lipogenic genes." (PMID 35198905, 2022).
type 2 diabetic (1 paper, 2022). "Our previous study confirmed that RNF186 expression was significantly increased in the liver tissues of HFD-induced obese mice and type 2 diabetic mice." (PMID 35198905, 2022).
RNF186 also shares sentences with these, for which no sentence is quoted: inflammation (3 papers); cancer (1); cardiovascular disease (1); hepatocellular carcinoma (1); liver steatosis (1); tumor (1).